HMGA1 (high mobility group AT-hook 1)
Diseases named in the same sentence as HMGA1 in open-access papers (continued):
Sharing a sentence is not in itself a finding about the gene and the disease.
liposarcoma (3 papers, 2018 to 2024). A usually painless malignant tumor that arises from adipose tissue. "In liposarcoma, HMGA1 overexpression was associated with trabectedin resistance, through a mechanism dependent on the activation of NFkB activity." (PMID 38758230, 2024). "Loss- and gain-of-function experiments by HMGA1-specific depletion and overexpression in dedifferentiated and myxoid liposarcoma cells showed the contribution of this oncogenic factor in cell proliferation, motility, invasion, and drug resistance." (PMID 29980789, 2018). "The immunohistochemical and RT-PCR analyses of 68 liposarcoma specimens revealed a significant high expression of HMGA1, at the protein and RNA levels, both in myxoid and dedifferentiated liposarcoma subtypes compared with differentiated ones." (PMID 29980789, 2018). "By the use of patient-derived and established cell lines from liposarcoma, as well as specimens from patient biopsies, we found that HMGA1 is involved in the progression of dedifferentiated and myxoid liposarcoma." (PMID 29980789, 2018). "Additionally, it has also been reported that HMGA1 regulated drug resistance in liposarcomas, through a mechanism involving E2F1." (PMID 38758230, 2024). "HMGA1 gene expression was high in CP0024 leiomyosarcoma 2D cell cultures, but similar to angiosarcoma (ICP059), sarcoma (SW982), and liposarcoma (93T449) cell lines." (PMID 38758230, 2024).
lung squamous cell carcinoma (3 papers, 2018 to 2022). "The HMGA1 expression level was not connected with the age of lung squamous cell carcinoma patients." (PMID 35805937, 2022).
medulloblastoma (3 papers, 2015 to 2020). A malignant, invasive embryonal neoplasm arising from the cerebellum. "c) Kaplan–Meier survival curve shows that increased levels of HMGA1 are associated with poor survival in Group 3 Medulloblastoma." (PMID 29880060, 2018). "d) Expression level of HMGA1 is highly correlated with the expression of the oncogene MYC in Group 3 Medulloblastoma." (PMID 29880060, 2018). "Additionally, western blot analysis of the four medulloblastoma groups showed the two HMGA1 isoforms expressed at higher levels in group 3 medulloblastoma." (PMID 29880060, 2018). "Western blot of HMGA1 isoforms in the four medulloblastoma subgroups." (PMID 29880060, 2018).
preeclampsia (3 papers, 2020 to 2024). Preeclampsia is a hypertensive disorder of pregnancy that is characterized by new-onset hypertension with proteinuria presenting after 20 weeks of gestation, and depending on mild or severe forms may initially present with severe headache, visual disturbances, and hyperreflexia. "HMGA1 promotes invasion of trophoblast cells and reduced levels of HMGA1 has been linked to pathogenesis of preeclampsia." (PMID 32268593, 2020).
retinoblastoma (3 papers, 2013 to 2017). A malignant tumor that originates in the nuclear layer of the retina. "In our previous study, high MIB-1 LI expression levels were associated with poor prognosis in retinoblastomas, and the increased expression of HMGA1 and HMGA2 correlated with the MIB-1 LI." (PMID 23935884, 2013). "The expression level of HMGA1 protein was found to be linked to the highly malignant phenotype of human cancers and a poor prognostic indicator, for instance for retinoblastomas." (PMID 23935884, 2013). "In our previous study, we identified miRNAs that were dysregulated by HMGA1 in retinoblastoma, further supporting the notion that HMGA1 is not only a marker for aggressive UM but also actively involved in gene regulation in this tumor." (PMID 23935884, 2013). "Our previous study found that high HMGA1 protein levels correlated with poor retinoblastoma prognosis." (PMID 23935884, 2013). "Interestingly, it was shown that the developmentally regulated gene HMGA1 is inversely correlated to let-7 in gastro-pancreatic carcinoma and retinoblastoma." (PMID 23798998, 2013).
skin cancer (3 papers, 2020 to 2024). "A previous study reported that HMGA1 negatively regulated autophagy in skin cancer cells." (PMID 32123163, 2020). "On the other hand, the transcription of ULK1 and ULK2 is repressed by the chromatin non-histone protein HMGA1 (high-mobility-group AT-hook 1) during the initiation and progression of malignant neoplasia such as skin cancer." (PMID 35159248, 2022).
Uterine leiomyoma (3 papers, 2015 to 2023). The presence of a leiomyoma of the uterus. "The results of this study imply that HMGA1 and PLAG1 rearrangements are likely to explain a small proportion of uterine leiomyomas with no mutations in the well‐established driver genes." (PMID 35822448, 2023). "Similarly, overexpression of HMGA1 has been found in uterine leiomyomas both with and without microscopically visible 6p21 aberration." (PMID 25621995, 2015).
uveal melanoma (3 papers, 2013 to 2022). A melanoma derived from melanocytes of the uveal tract. "Previous studies have reported that the PI3K/AKT/MMP-9 pathway is a unique downstream pathway of HMGA1, which is critical for uveal melanoma cell proliferation, survival, and migration." (PMID 36479041, 2022). "Nuclear expression of HMGA1 was detected in 39 uveal melanomas (44%), whereby 25 of them (28% of the total of 89 patient samples) expressed it a high levels (marked 4+, 3+ and 2+ as described in detail in Materials & Methods)." (PMID 23935884, 2013). "We evaluated HMGA1 expression in 89 primary uveal melanomas (UM) by immunohistochemistry to determine the clinicopathological and prognostic value of HMGA1 in UM after adjusting for other prognostic variables." (PMID 23935884, 2013). "Clinicopathological features, tumor markers, HMGA1, and uveal melanoma patients' survival." (PMID 23935884, 2013). "In uveal melanoma specimens, immunopositivity for HMGA1 showed a clear nuclear staining." (PMID 23935884, 2013). "Clinical, pathologic characteristics according to HMGA1 alterations in uveal melanoma." (PMID 23935884, 2013).
Alzheimer disease (2 papers, 2015 to 2019). A progressive, neurodegenerative disease characterized by loss of function and death of nerve cells in several areas of the brain leading to loss of cognitive function such as memory and language. "It was reported that HMGA1 promotes cancer stem cell properties and plays a role in the pathogenesis of Alzheimer’s disease." (PMID 31888570, 2019).
Barrett esophagus (2 papers, 2016 to 2024). Esophageal lesion lined with columnar metaplastic epithelium which is flat or villiform. "Conversely, HMGA1, but not HMGA2, was overexpressed in esophageal adenocarcinoma samples." (PMID 27027341, 2016).
carcinoma in situ (2 papers, 2022). "HMGA1 protein has been found to be present in increased amounts in metaplasia, dysplasia, and carcinoma in situ of the bronchial epithelium." (PMID 35805937, 2022). "HMGA1 protein was found in an increased amount in metaplasia, dysplasia, and carcinoma in situ of the bronchial epithelium." (PMID 35805937, 2022). "Previously, it was observed that a number of positively staining cells for HMGA1 by immunohistochemistry was lower in metaplasia and higher in dysplasia and carcinoma in situ of the bronchial epithelium which could suggest that HMGA1 expression increases during carcinogenesis progress." (PMID 35948739, 2022).
COVID-19 (2 papers, 2022). A disease caused by infection with severe acute respiratory syndrome coronavirus 2. "The existence of low levels of HMGA1 gene may play a key role as a risk factor for COVID-19 patients by triggering inflammatory pathways and atherosclerosis." (PMID 35181720, 2022). "Low levels of HMGA1 in airway tissues are also associated with smoking and COPD24, connecting cardio and respiratory diseases with COVID-19 severity." (PMID 35181720, 2022). "To conclude, DNMT1, HMGA1, and HMGA2 might be central TFs in the TF–gene regulatory network in COVID-19/NSCLC." (PMID 35721149, 2022).
diabetic retinopathy (2 papers, 2018 to 2019). "Thus, the protective effect of the HMGA1 rs139876191 variant on diabetic retinopathy may also be mediated through a process that involves inactivation of FoxO1 gene and protein expression." (PMID 29052178, 2018). "In particular, it has been demonstrated that HMGA1 regulates VEGFA gene expression in diabetic retinopathy and, by interacting with HIF1, in 3T3 L1 adipocytes." (PMID 31311575, 2019).
gastric adenocarcinoma (2 papers, 2021 to 2022). "Previously, HMGA1 expression was analyzed by immunohistochemistry in a hospital series (n = 323) comprising single hospital gastric adenocarcinoma cases (stages I to IV) with clinicopathologic and therapeutic datasets." (PMID 36568211, 2022). "HMGA1 expression was analyzed by immunohistochemistry in a single hospital series (n = 323) of gastric adenocarcinoma cases (stages I to IV) with clinicopathological and treatment data." (PMID 35049679, 2021). "Thus, the aim of this study was to investigate the clinical value of HMGA1 expression in a robust series of gastric adenocarcinoma cases with clinicopathological and treatment data." (PMID 35049679, 2021).
gastric tumor (2 papers, 2021 to 2022). "In addition, the expressions of hsa_circ_0091994 and HMGA1 in clinical gastric tumor tissues were notably upregulated, while the level of miR-324-5p was downregulated compared with that in adjacent tissues." (PMID 34483139, 2021). "Additionally, a positive correlation between HMGA1 and LINC00152 in stomach tumors was detected from the GEPIA database." (PMID 35014092, 2022).
head and neck cancer (2 papers, 2014 to 2019). A primary or metastatic malignant neoplasm affecting the head and neck. "We systematically classify the expression level and the clinical prognosis of HMGA1 in head and neck cancers, thoracic cancers, abdominal cancers and reproductive system cancers." (PMID 30614613, 2019). "According to recent findings, HMGA1 is a potential biomarker for clinical diagnosis in head and neck cancer." (PMID 30614613, 2019). "Contrary to this, HMGA1 expression was also reported to be increased in head and neck carcinomas analysed via semi-quantitative RT-PCR and immunohistochemistry when compared to healthy mucosa samples." (PMID 25245141, 2014). "Previous studies analysing the HMGA1 expression in human head and neck cancers reported contradictory results, showing no statistical significant deregulations as well as increased expression of HMGA1 in OSCC, matching our results in both species." (PMID 25245141, 2014).
HIV-1 infection (2 papers, 2015 to 2016). The type species of lentivirus and the etiologic agent of acquired immunodeficiency syndrome (AIDS). "HMGA1 has been previously implicated in HIV-1 infection as a host cellular co-factor recruiting the nucleosome remodeling complex SWI/SNF to the HIV-1 LTR, being involved in HIV-1 splice site regulation and contributing to the HIV-1 pre-integration complex." (PMID 26117853, 2015). "Among the cellular target genes regulated by HIC1, CTIP2 and HMGA1 are several, which have been reported to be involved in HIV-1 infection." (PMID 27725726, 2016). "In the case of HIV-1 infection, HMGA1 affects viral gene expression by at least two different mechanisms: A direct binding to HIV-1 TAR, preventing Tat-mediated transcription activation and the recruitment of CTIP2 and CTIP2-inactivated P-TEFb complex." (PMID 26117853, 2015). "Taken together, HMGA1 depicts a host cellular co-factor involved in a large variety of aspects during HIV-1 infection, some of which may synergize, especially those involved in HIV-1 transcription regulation." (PMID 26117853, 2015). "Thus, also in the case of HIV-1 infection, the targeting of HMGA1 function by 7SK Loop2 could contribute to the reactivation of latent HIV-1 reservoirs, which could subsequently be eradicated by HAART." (PMID 26117853, 2015).
liver cirrhosis (2 papers, 2023 to 2024). "High mobility group AT-hook 1 (HMGA1), a non-histone nuclear protein, has been found to recruit protein PGC1α to enhance HBV replication and antigen production through HBV EII/Cp promoter activation, which is associated with liver cirrhosis and HCC oncogenesis." (PMID 38774408, 2024).
lymphoid tumor (2 papers, 2011 to 2013). "HMGA1 functions as a potent oncogene in cultured cells and induces aggressive lymphoid tumors in transgenic mice." (PMID 22053823, 2011). "In preliminary studies, we found that crossing the HMGA1 transgenics with mice null for the p50 subunit of NFκB results in an increase in lymphoid tumor burdens (Belton & Resar, unpublished data)." (PMID 22053823, 2011). "To determine if these results are relevant to human tumors, we knocked-down HMGA1 in human T-cell leukemia cells and identified a subset of genes dysregulated in both the transgenic and human lymphoid tumors." (PMID 22053823, 2011).
multiple myeloma (2 papers, 2021 to 2024). "Curiously, trabectedin treatment seems to upregulate E2F1 in multiple myeloma, which supports the hypothesis that the HMGA1/E2F1 axis could be activated as a mechanism of resistance after trabectedin." (PMID 38758230, 2024).
myelofibrosis (2 papers, 2020 to 2025). A partial or complete replacement of the bone marrow stroma by fibrous tissue. "In JAK2-V617F transgenic mice, the loss of just a single Hmga1 allele was sufficient to dampen erythrocytosis and thrombocytosis while preventing splenomegaly, osteosclerosis, and myelofibrosis." (PMID 40076747, 2025). "We discovered that the High Mobility Group A1 (HMGA1) gene is up-regulated with MPN progression in patients and required for evolution into myelofibrosis (MF) or acute myeloid leukemia (AML) in preclinical models." (PMID 40076747, 2025).
myxoid liposarcoma (2 papers, 2018 to 2024). A liposarcoma characterized by the presence of round non-lipogenic primitive mesenchymal cells and small signet ring lipoblasts within a myxoid stoma with a branching vascular pattern. "In fact, in this study, it was shown that HMGA1 depletion in combination with trabectedin treatment had an additive effect on myxoid liposarcoma cell death, which demonstrated that this epigenetic transcriptional factor plays an important role in the mechanisms of resistance to trabectedin." (PMID 38758230, 2024).
oral cancer (2 papers, 2014 to 2016). "HMGA2 was found to be expressed at the invasive front of oral carcinomas leading to the conclusion that –in contrast to HMGA1- HMGA2 immunostaining could be a potential prognostic determinant in stratifying patients into risk groups." (PMID 25245141, 2014).
renal carcinoma (2 papers, 2022 to 2024). A carcinoma arising from the epithelium of the renal parenchyma or the renal pelvis. "To determine the effect of PTBP3 on HMGA1 mRNA, we assessed the expression of HMGA1 in renal cancer cells with PTBP3 overexpression or knockdown." (PMID 38405614, 2024). "Studies have confirmed that HMGA1 is mainly expressed in the nucleus of renal carcinoma cells and induces anoikis." (PMID 35864955, 2022). "In the present study, PTBP3 promoted HMGA1 expression and renal cancer cell migration and invasion." (PMID 38405614, 2024). "Additionally, PTBP3 promotes the migration and invasion abilities of renal cancer cells by regulating HMGA1 expression in vivo." (PMID 38405614, 2024). "Furthermore, miR-328-5p, miR-31-5p and miR-195 have the capacity to prevent the progression of renal carcinoma by downgrading the expression levels of HMGA1 in the form of cell cycle stasis and EMT reversal 129-131." (PMID 35864955, 2022).
renal cell carcinoma (2 papers, 2021 to 2024). "IGF2BP3 silencing decreased HMGA1 protein levels accordingly in PTBP3 overexpressing renal cell carcinoma cells." (PMID 38405614, 2024). "HMGA1 overexpression restored the effect of PTBP3 downregulation on the proliferation, migration, and invasion of renal cell carcinoma in vivo." (PMID 38405614, 2024). "Similarly, HMGA1 overexpression restored the effect of PTBP3 downregulation on proliferation and pulmonary metastasis of renal cell carcinoma cells in vitro." (PMID 38405614, 2024).
respiratory failure (2 papers, 2019 to 2021). The significant impairment of gas exchange within the lungs resulting in hypoxia, hypercarbia, or both, to the extent that organ tissue perfusion is severely compromised. "We have previously demonstrated that Hipk2-null (Hipk2-KO) mice present cerebellar alterations associated with psychomotor abnormalities and that the double ablation of HIPK2 and its interactor HMGA1 causes perinatal death due to respiratory failure." (PMID 34361060, 2021). "Here, we report that Hmga1/Hipk2 DKO mice die within 12 h of life for respiratory failure, likely owing to impaired lung development associated to a drastic reduction in surfactant proteins, whose expression is positively regulated by both HMGA1 and HIPK2." (PMID 31582725, 2019). "About 50% of these Hmga1/Hipk2 double knock-out (DKO) mice die within 12 h of life (P1) for respiratory failure." (PMID 31582725, 2019). "According to these results, the proper expression of surfactant genes requires in vivo the presence of both the HMGA1 and HIPK2 proteins, and their lack mainly accounts for the atelectasis condition with a respiratory failure of DKO mice at birth." (PMID 31582725, 2019).
sarcoma (2 papers, 2011 to 2024). A usually aggressive malignant neoplasm of the soft tissue or bone. "Nevertheless, HMGA1 was the factor that sustained the most significant associations with trabectedin outcome, mostly in patients diagnosed with L-sarcomas and in particular in leiomyosarcoma." (PMID 38758230, 2024). "In L-sarcomas, HMGA1 strong intensity was significantly associated with worse PFS [3.2 months (95% CI 2.0–4.4) vs. 5.6 months (95% CI 4.1–7.1), p = 0.008] and worse OS [10.5 months (95% CI 0.8–20.2) vs. 21.8 months (95% CI 16.0–27.6), p = 0.017]." (PMID 38758230, 2024). "In in vivo studies, the combination of rapamycin with trabectedin downregulated HMGA1 expression and stabilized tumor growth of 3-methylcholantrene-induced sarcoma-like models." (PMID 38758230, 2024). "Trabectedin plus mTOR inhibitors are active in preclinical models of sarcoma, downregulating HMGA1 expression levels and stabilizing tumor growth." (PMID 38758230, 2024). "The up-regulation of inflammatory pathways during HMGA1-induced tumorigenesis is also consistent with our previous studies demonstrating that anti-inflammatory agents (sulindac and celecoxib) interfere with sarcomas in our HMGA1 transgenics." (PMID 22053823, 2011). "Moreover, since some histologies were underrepresented in our series of cases, we cannot exclude that HMGA1 overexpression may have an impact on the efficacy of trabectedin and patient survival in other sarcoma subtypes, besides leiomyosarcomas." (PMID 38758230, 2024). "Nonetheless, the extension of the expression of HMGA1 did not correlate significantly with survival in L-sarcomas." (PMID 38758230, 2024). "In non-L-sarcomas, neither expression nor the intensity of HMGA1 immunostaining correlated significantly with PFS or OS." (PMID 38758230, 2024).
serous ovarian cancer (2 papers, 2022). "Evaluation of urinary HMGA1 in a study limited to serous ovarian cancer yielded AUCs of 0.86 and 0.88 for grade 1/2 and grade 3 cancers, respectively." (PMID 35166350, 2022).
small cell carcinoma (2 papers, 2009 to 2022). A neuroendocrine carcinoma composed of small malignant cells which are often said to resemble "oat cells" under the microscope. "HMGA1 upregulation was observed in small cell carcinoma, but without statistical significance." (PMID 35805937, 2022).